RARB (retinoic acid receptor beta)
Diseases named in the same sentence as RARB in open-access papers (continued):
Sharing a sentence is not in itself a finding about the gene and the disease.
gastric cancer (9 papers, 2003 to 2026). A primary or metastatic malignant neoplasm involving the stomach. "In various cancers, including gastric cancer, RARβ gene expression is silenced through extensive promoter methylation in approximately 64% of gastric cancers which has been linked to worse prognosis and aggressive disease." (PMID 41280003, 2025). "In gastric cancer, high expression levels of RARα/RARβ/RARγ/RXRβ transcripts are associated with poor clinical and molecular characteristics as well as with reduced overall-survival." (PMID 39323992, 2024). "In fact, high levels of RARα, RARβ, RXRα and RXRβ are associated with unfavorable prognostic clinical and pathological characteristics of gastric cancer, such as stage-IV and “de novo” metastatic disease." (PMID 39323992, 2024). "Finally, we established associations of the RARα, RARβ, RARγ and RXRβ levels with a detrimental effect on the overall-survival of gastric cancer patients." (PMID 39323992, 2024). "Among the pathways disrupted, retinoic acid signaling is of particular interest, as retinoid receptors such as retinoic acid receptor α and RARβ are frequently hypermethylated and repressed in EBV-associated gastric cancer." (PMID 41665354, 2026). "Taken together, our data support the idea that the tumor levels of RARα, RARβ, RARγ and RXRβ mRNAs are potential determinants of a low overall-survival rate in gastric cancer." (PMID 39323992, 2024). "The results of the RAR-GASTRIC study demonstrate that gastric cancer specimens contain significant amounts of RARα/RARβ/RXRα/RXRβ mRNAs." (PMID 39323992, 2024). "In this single-institution/retrospective clinical and translational study (RAR-GASTRIC), we define the expression of RARα, RARβ, RARγ, RXRα, RXRβ and RXRγ in stomach tumors with the use of archival tissue samples obtained from gastric cancer patients." (PMID 39323992, 2024). "In this study, we determine the RNA expression of the six isoforms of Retinoic-Acid-Receptors (RARα/RARβ/RARγ/RXRα/RXRβ/RXRγ) in view of their potential use as gastric cancer progression markers and/or therapeutic targets." (PMID 39323992, 2024). "Our data are consistent with the idea that RARα, RARβ, RARγ and RXRβ represent potential prognostic markers and therapeutic targets of gastric cancer." (PMID 39323992, 2024). "The work supports the idea that RARα, RARβ, RARγ and RXRβ represent potential prognostic markers and actionable therapeutic targets in the context of the personalized treatment of gastric cancer." (PMID 39323992, 2024). "To identify the RAR isoform(s) underlying the anti-proliferative action of the retinoid, initially, we evaluated the constitutive expression of RARα, RARβ, RARγ, RXRα, RXRβ and RXRγ mRNAs in our gastric-cancer cell-lines." (PMID 37951921, 2023). "Promoter hypermethylation was also detected in 64% of gastric carcinoma tissues with reduced RARβ expression, and mainly in poorly differentiated type of gastric carcinoma." (PMID 32012980, 2020). "CDH1 and RARβ promoter hypermethylation was more frequently observed in the diffuse scattered type of gastric cancer." (PMID 25997695, 2015). "The promoter hypermethylation of retinoic acid receptor β (RARβ) is observed in 64% of cases of gastric cancer." (PMID 25997695, 2015). "In a previous report on RARs' and RXRs' Northern mRNA expression level of gastric cancer cell lines, enhanced expression of RARα/RARγ was observed in SC-M1 cells and enhanced RARβ level was found in TSGH cells." (PMID 12671705, 2003). "Finally, we observe a worse overall-survival in gastric cancer patients characterized by high RARα/RARβ/RARγ/RXRβ mRNA levels." (PMID 39323992, 2024). "Based on our results, it is reasonable to assume that high expression levels of RARα, RARβ, RXRα and RXRβ have a negative impact on gastric cancer patients’ overall-survival." (PMID 39323992, 2024).
microphthalmia (9 papers, 2018 to 2026). Congenital or developmental anomaly in which the eyeballs are abnormally small. "Here, we report the identification of a de novo noncoding RARB gene variant (c.157+1895G>A) associated with a complex microphthalmia phenotype and significant global developmental delay." (PMID 39450403, 2024). "Loss- or gain-of-function RARB coding variants have been associated with microphthalmia, coloboma, and anterior segment defects." (PMID 39450403, 2024). "We focused specifically on the RARB mutation for further investigation as this mutation has been recently reported in a patient with syndromic microphthalmia." (PMID 31816153, 2020). "In recent reports, patients carrying RARB mutations are described with a severe syndromic phenotype affecting several organ systems and including coloboma, microphthalmia, anophthalmia, cardiac defects, progressive motor impairment, pulmonary hypoplasia, and diaphragmatic hernia." (PMID 31816153, 2020). "We identified a de novo variant c.157+1895G>A located within a conserved region (CR1) in the first intron of RARB in an individual with complex microphthalmia and significant global developmental delay." (PMID 39450403, 2024). "Mutations in RARB have been identified in patients with syndromic MAC [i.e., pulmonary hypoplasia/agenesis, diaphragmatic hernia/eventration, anophthalmia/microphthalmia, and cardiac defect (PDAC)]." (PMID 31796115, 2019). "The most plausible developmental link is disruption of the retinoic acid signaling pathway, where mutations in STRA6 and RARB give rise to the PDAC/Matthew–Wood syndrome, characterized by microphthalmia, pulmonary hypoplasia/agenesis, and diaphragmatic defects." (PMID 40941759, 2025). "Gain-of-function RARB variants and increased FOXC1 gene dosage via gene duplication have both been associated with developmental ocular phenotypes similar to those observed in the individual presented here, including microphthalmia, anterior segment anomalies, and congenital glaucoma." (PMID 39450403, 2024). "However, RARB had not been specifically related to colobomas until a subsequent study published after completion of patient 1’s exome more clearly linked heterozygous RARB variants to coloboma without microphthalmia, strengthening the link between this variant and the patient’s phenotype." (PMID 35937981, 2022).
thyroid cancer (9 papers, 2009 to 2025). "miRNA-106a, directly targeting RARB, associates with the viability, apoptosis, differentiation and the iodine uptake function of thyroid cancer cell lines by regulating MAPK signaling pathway in vitro." (PMID 27342319, 2016). "According to the Human Protein Atlas, RARβ expression is high in the thyroid while RARβ expression is reduced in thyroid carcinomas." (PMID 35216288, 2022). "In this study we showed that inhibition of miR-146a and miR-146b results in restoration of RARB and in decrease of proliferation rates of thyroid cancer cells." (PMID 27011326, 2016). "Further, in order to investigate the potential mechanism of miR-106a-RARB regulating the apoptosis level of thyroid cancer cells, 8505C-miR106a(−) cells with inhibition of ASK1 by NQDI-1 were used." (PMID 27342319, 2016). "In order to investigate the potential mechanism of miR-106a-RARB regulating the viability of thyroid cancer cells, 8505C-miR106a(−) cells with overexpression of MAP3K2 (MEKK2) were used." (PMID 27342319, 2016). "The fact that RARB is diminished in a large number of cancers, including thyroid cancer, shows its importance for cellular homeostasis and indicates its tumor suppressive role, which is exerted mainly by the action of its ligand, retinoic acid." (PMID 27011326, 2016). "Retinoic acid is a promising tool in adjuvant cancer therapies, including refractory thyroid cancer, and its biological role is mediated by the retinoic acid receptor beta (RARβ)." (PMID 27011326, 2016). "miR-106a-RARB promoted viability of thyroid cancer cells by regulating MEKK2-ERK1/2 and MEKK2-ERK5 pathway." (PMID 27342319, 2016). "RARβ has been shown to be associated with thyroid cancer recurrence; however, in our meta-analysis, it was not possible to examine this concept by subgroup analyses due to the low sample size and lack of data related to recurrence in the identified studies." (PMID 28926589, 2017). "Similarly, a defective RARB promoter was demonstrated to lead to partial insensitivity of thyroid cancer cells." (PMID 29131833, 2017). "Together with the results of cell viability assays and western blotting, these data demonstrated that miR-106a-RARB could increase the viability of thyroid cancer cells by activating MEKK2-ERK1/2 and MEKK2-ERK5 pathway." (PMID 27342319, 2016). "Low levels of RARβ are potentially one of the mechanisms leading to reduced uptake of iodine by tumor cells and ineffectiveness of radioiodine therapy, significantly worsening the prognosis of thyroid cancer patients." (PMID 27011326, 2016). "By increasing RARB levels, microRNA inhibitors may become part of an adjuvant therapy in thyroid cancer patients." (PMID 27011326, 2016). "miR-106a-RARB inhibited apoptosis of thyroid cancer cells by regulating ASK1-p38 pathway." (PMID 27342319, 2016). "Together with the results of apoptosis flow cytometry analysis and western blotting, these data demonstrated that miR-106a-RARB could decrease apoptosis of thyroid cancer cells by inhibiting ASK1-p38 pathway." (PMID 27342319, 2016). "By restoring RARB levels, microRNA inhibitors may become part of an adjuvant therapy in thyroid cancer patients." (PMID 27011326, 2016). "In addition, the influence of RA, the ligand of RARB, on 125I uptake in these models was also studied and the results demonstrated that RA could increase the ability of iodine uptake in thyroid cancer cells under the existence of RARB." (PMID 27342319, 2016). "In agreement with this, RARB was found to suppresses MAPK kinase kinase 2 to inactivate the MAPK signaling, and the RARB downregulation by miRNA-106a led to MAPK activation and increased the apoptosis of thyroid cancer cells." (PMID 35611845, 2022). "In the current study, miR-106a, directly targeting RARB, might promote viability of thyroid cancer cells by activating MEKK2-ERK1/2 and MEKK2-ERK5 pathway and increase the apoptosis of thyroid cancer cells by inhibiting ASK1-p38 pathway." (PMID 27342319, 2016).
thyroid cancer (continued). "Moreover, we also found that miRNA-106a-RARB could regulate the expression of NIS, TSHR and alter the iodine uptake function of thyroid cancer cells through MAPK signaling pathway." (PMID 27342319, 2016). "Moreover, miR-106a-RARB could regulate the expression of sodium iodide symporter, TSH receptor and alter the iodine uptake function of thyroid cancer cells." (PMID 27342319, 2016).
acute promyelocytic leukemia (8 papers, 2020 to 2025). An aggressive form of acute myeloid leukemia (AML), characterized by arrest of leukocyte differentiation at the promyelocyte stage, due to a specific chromosomal translocation t(15;17) in myeloid cells. "RARα and RARβ are associated with acute promyelocytic leukemia (APL) and squamous cell malignancies, where they play a role in regulating cell proliferation and differentiation." (PMID 40430363, 2025). "Over the years, several other types of rare X-RARA fusions have been described, while recently, oncogenic fusion proteins involving other retinoic acid receptors (RARB or RARG) have been associated to very rare cases of acute promyelocytic leukemia." (PMID 32295268, 2020). "Notably, it was found that the fusion gene FNDC3B::RARB was related to all-trans retinoic acid resistance in acute promyelocytic leukemia (APL), which indicated the potential role of RARB in leukemia treatment." (PMID 39723714, 2025). "Among the retinoic acid receptors (RARα, RARβ and RARγ), the co-administration of ATRA with arsenic trioxide represents a breakthrough front-line treatment for acute promyelocytic leukemia, acting via modulation of RARα activity, offering new avenues for effectively managing the disease." (PMID 39175546, 2024).
bladder cancer (8 papers, 2008 to 2025). "Specific genes such as RASSF1A, RARB, BAMBI and the SFRP family have been associated with higher grade and higher stage bladder cancer." (PMID 20808801, 2010). "In addition, methylated RARβ was frequently found in bladder cancer tissues and urine samples from bladder cancer patients, suggesting its utility as a urine marker." (PMID 26770009, 2015). "Clinical and histopathological prevalence parameters and DNA methylation pattern for RARB and RASSF1A genes in 49 fresh urinary bladder carcinoma tissues." (PMID 18702824, 2008). "Accuracy estimatives from MSP for RARB and RASSF1A genes observed in primary and/or previous recurrence of urinary bladder carcinoma and respective washout." (PMID 18702824, 2008). "Moreover, other molecular modifications associated with T24 TCC line and/or bladder cancer tissues have been found and they can be correlated with ATRA resistance as RARβ silencing by aberrant methylation, and the absence of the estrogen receptor, or rather estrogen receptor negative (ER-)." (PMID 32756427, 2020).
colon carcinoma (8 papers, 2013 to 2024). "Human colon cancer cell lines with increased expression of RARβ were more sensitive to tretinoin induced apoptosis." (PMID 38350880, 2024). "RARB is also found to be downregulated in several types of cancer, including colon cancer, and it has been demonstrated that silencing of RARB correlates with impaired RARα-signaling." (PMID 35275975, 2022). "It has been shown that down-regulation of sphingosine kinase 2 increases ATRA-induced RARβ expression, arrests the cell cycle in G1 phase, and induces apoptosis in colon cancer cells." (PMID 36135086, 2022). "Two independent studies showed that HT-29 colon cancer cell response to ATRA was minimal despite a significant elevation in the RARβ expression." (PMID 32456134, 2020). "Later studies correlated the ATRA resistance to the impaired RARβ in gastric, and colon cancers." (PMID 32012980, 2020). "Moreover, we found that RARα, RXRα, and RXRβ showed higher expression, while RARβ showed lower expression in colon carcinoma cells (poorly differentiated), the normal colon (highly differentiated) being the control (data not shown)." (PMID 25881300, 2015). "In the current study, we show that ATRA’s ability to induce MUC-2 expression in SW480 colon cancer cells might also involve CysLT2R signaling, as the effect can be reduced by either a CysLT2R inhibitor or by RARα siRNA alone or a combination of RARα and RARβ siRNA." (PMID 23829413, 2013). "Despite the importance of COUP-TF in the RARβ expression, its role in gastric, hepatic and colon cancer has not yet been investigated." (PMID 32012980, 2020). "In addition, S1P antagonized the effects of ATRA on colon cancer cell proliferation, ATRA-stimulated RARβ expression, G1 phase arrest and apoptosis induction, and these events were reversed by down-regulation of SphK2." (PMID 32456134, 2020).
colorectal cancer (8 papers, 2007 to 2025). A primary or metastatic malignant neoplasm that affects the colon or rectum. "We were able to validate previous findings describing frequent hypermethylation events of EPHA7, MGMT and MLH1 in colorectal cancer patients, RARB in prostate tumors, and CASP8 in glioblastoma." (PMID 28581523, 2017).
head and neck squamous cell carcinoma (8 papers, 2007 to 2025). A squamous cell carcinoma that arises from any of the following anatomic sites: lip and oral cavity, nasal cavity, paranasal sinuses, pharynx, larynx, and salivary glands. "Decreased RARβ expression was found in head and neck squamous cell carcinoma, premalignant oral lesions, and esophageal squamous cell carcinoma." (PMID 18166136, 2007). "Moreover, 26 induced expression of the NR2F1-regulated genes SOX9, RARβ, and p27 in chicken embryo chorioallantoic membrane tumors, and inhibited tumor growth and metastasis of head and neck squamous-cell carcinoma (HNSCC) in mice." (PMID 40046426, 2025). "In PCa and head and neck squamous cell carcinoma (HNSCC) models, NR2F1 induced a dormant phenotype by regulating the H3K4me3 and H3K27me3 epigenetic marks in the promoter of SOX9 and RARβ." (PMID 34208521, 2021). "The orphan nuclear receptor (NR2F1) regulates tumor cell dormancy in head and neck squamous cell carcinoma (HNSCC) by coordinating the hypermethylation of H3 histone proteins (H3K27, H3K9, and H3K4), bounded to SOX9, RARβ, and CDK inhibitors to inhibit cell proliferation." (PMID 38994941, 2024).
hepatocellular carcinoma (7 papers, 2013 to 2025). A malignant tumor that arises from hepatocytes. "In support of our observation, a previous report has shown that RA specifically increases RARB mRNA level in human hepatoma cells." (PMID 40591414, 2025). "Previous studies on modification of RARβ expression in hepatoma cells revealed that in the presence of RARβ the cells cease proliferation and begin differentiation." (PMID 27011326, 2016). "Recent studies in human hepatocellular carcinoma cells showed that Nur77 and RARB interaction might stabilize Nur77 and sustain its expression level." (PMID 25970467, 2015). "Furthermore, RARB has been shown to interact with Nur77 in human hepatocellular carcinoma cells and thus leads to apoptosis." (PMID 25970467, 2015). "ACR treatments on hepatoma cell lines can suppress growth through inducing of apoptosis via caspase-3 cleavage, inhibiting RXRα phosphorylation by suppressing Ras-MAPK pathway, up-regulating RARβ expression, and promoting cell cycle arrest by increasing cellular levels of p21CIP1." (PMID 24379011, 2013).